ATM (ATM serine/threonine kinase)
Diseases named in the same sentence as ATM in open-access papers (continued):
Sharing a sentence is not in itself a finding about the gene and the disease.
breast cancer (continued). "Additionally, pathogenic alterations in PALB2, ATM, CHEK2, and NBN are correlated with an increased risk for breast cancer and/or other cancers, whereas other genes such as BRIP1, RAD51C, and RAD51D are associated with an increased ovarian cancer risk." (PMID 32733558, 2020). "In addition, germline mutations in DNA damage repair genes such as ATM and CHEK2 are also associated with an increased risk of breast cancer." (PMID 32091409, 2020). "The fact that heterozygous ATM mutation carriers have only a slight increase in breast cancer risk and no increased risk for other solid tissue malignancies despite ATM’s profound influence on genomic instability is surprising." (PMID 32566127, 2020). "In addition, we also analyzed HERVs that were associated, by localization, with breast cancer development genes (BRCA1, CCND1, ATM, NBS1/NBN, RAD50, KRAS, PI3K/PIK3CA)." (PMID 33194615, 2020). "MiR-302b by regulating E2F1/ATM axis could enhance breast cancer cell sensitivity to cisplatin and promote G1/S arrest in BC cells." (PMID 33330110, 2020). "Other breast cancer susceptibility genes have recessive phenotypes associated with biallelic PVs, including Fanconi Anemia for BRCA2 and PALB2, Ataxia Telangiectasia for ATM, and Nijmegen Breakage Syndrome for NBN." (PMID 31993860, 2020). "For example, PVs in ATM and BRCA1 were significantly associated with >twofold increased risk for colorectal cancer and PVs in RAD51D and CDKN2A were significantly associated with >twofold increased risk for breast cancer." (PMID 31406321, 2020). "Multivariate analysis showed that low ATM was associated with poor OS independent of tumor size and lymph node status, but only in HR- breast cancer." (PMID 33224881, 2020). "In summary, we provide compelling evidence demonstrating that TAIII induces cell cycle arrest and apoptosis through ATM/Chk2 and p38 MAPK signaling pathways, associating with induction of DNA damage, which offer a promising anti-tumor agent against breast cancer." (PMID 33628174, 2020). "Thus, we checked the ATP levels in CSCs derived from oxidized ATM activated or inactivated, and endogenous ATM knocked down breast cancer cells." (PMID 32641713, 2020). "Interestingly, combined PI3K and PARP inhibition have also provided more efficient responses in BRCA1-deficient breast cancer cells and dual ATR and BCR inhibition has also been proven to be synergistic in ATM-defective CLL cells." (PMID 31974435, 2020). "Within the group of 46 women diagnosed with TNBC between 45 and 60 years of age but without a significant family history of breast cancer, three (6.5%) harbored mutations in ATM (n = 1), BAP1 (n = 1), or BRCA2 (n = 1)." (PMID 33302456, 2020). "In this sense treatment with ATM inhibitor KU55933 restored radiosensitivity of the BCSC subpopulation, suggesting that targeting ATM signaling could be effective to eradicate of radioresistant breast cancer cells." (PMID 32660072, 2020). "None of the CpG sites in ATM were statistically significantly associated with breast cancer risk in our study." (PMID 31101124, 2019). "In a group of Polish women with TNBC unselected for family history, one woman out of 158 with TNBC harbored a mutation in ATM whereas no ATM mutations were detected in 44 women with non-TNBC hereditary breast cancer." (PMID 31379942, 2019).
breast cancer (continued). "A recent systematic review summarized the most promising findings of DNA methylation as a biomarker of disease, concluding that hypermethylation at BRCA1 and RASSF1A gene promoters, and hypermethylation of the body of the ATM gene were more common in breast cancer cases." (PMID 31101124, 2019). "It is interesting that heterozygous mutations in other genes in this pathway (i.e., BRCA1, BRCA2, CHEK2, NBN, ATM) predispose to breast cancer, but a heterozygous mutation in BLM does not appear to be pathogenic for breast cancer." (PMID 31614901, 2019). "The highest number of VUS was observed in ATM (n = 6), a clinically actionable breast cancer gene." (PMID 31780696, 2019). "Our previous study showed that hypoxia, a common feature of solid tumors, could induce VEGFA expression and angiogenesis in breast cancer cells and tumor-bearing mice by activating the ATM–SerRS pathway." (PMID 31766690, 2019). "Of the 9 CpG sites located in the body of ATM, only two were associated with breast cancer risk in the direction previously reported and there was no enrichment (P = 0.26)." (PMID 31101124, 2019). "We hypothesize that variants in the ATM, H2AFX and MRE11 genes may modulate a predisposition to breast cancer." (PMID 29678143, 2018). "Thus far we had observed that neoantigen load agreed well with CTL invasion in colorectal cancer and phosphorylated ATM was a larger determinant in breast cancer, but it remained unclear how generalizable these findings are." (PMID 29615613, 2018). "Expression of ZEB1 is increased in breast cancer and positively correlates with ATM protein levels." (PMID 29352223, 2018). "Three genes with evidence for association with breast cancer are on the eMERGEseq platform (ATM, CHEK2, PALB2), but were not used to develop outcomes." (PMID 30011878, 2018). "In this study, we hypothesize a role of variants in the ATM, H2AFX and MRE11 genes in determining breast cancer (BC) susceptibility." (PMID 29678143, 2018). "Our findings partly verified the hypothesis of this study, by showing that ATM gene might be a candidate gene of breast cancer in Han Chinese." (PMID 29691986, 2018). "Four genes (six associations: BRCA1, BRCA2, and ANK2 in ovarian cancer, BRCA1, BRCA2, and ATM in breast cancer) were significant in at least one individual cancer type (FDR = 0.2, referred to as ‘individual cancer ALFRED genes’) and all four genes were also significant in the pan-cancer analysis." (PMID 29973584, 2018). "By this approach, we identified loss‐of‐function mutations in 6/20 (30%) probands, five of which occurred on BRCA1, CHEK2, and ATM and are esteemed to be risk‐relevant according to our studies, while a novel RAD50 truncating mutation is most likely unrelated to breast cancer." (PMID 29271107, 2018). "Importantly, the correlation between ZEB1 and ATM, as well as the other seven target genes, were demonstrated by TCGA database analysis, highlighting a predominant role for ZEB1 in inducing ATM expression in breast cancer cells." (PMID 29352223, 2018). "Notably, levels of p-ATM increased indicating DNA instability in breast cancer cells after GTN treatment." (PMID 30598998, 2018).
breast cancer (continued). "We demonstrate that, in breast cancer cells, ATM and ATG4C are essential drivers of mammosphere formation, suggesting that their targeting may improve current approaches to eradicate breast cancer cells with a stem-like phenotype." (PMID 28423511, 2017). "This is in contrast to the ERα-mediated repression of ATM found in breast cancer cells." (PMID 29137421, 2017). "Interestingly, few pathogenic variants were identified in ATM and BRCA1, which are commonly mutated in female familial breast cancer." (PMID 28008555, 2017). "The downstream target of ATM, CHK2, has been found instead mutated in low rate in several kinds of cancer and in particular in hereditary cancers (CHK2 1100delC protein-truncating mutation confers a twofold increased risk of breast cancer)." (PMID 28356161, 2017). "The strongest association with breast cancer risk among BRCA1 carriers was observed for rs6589007, located at 11q22.3 in intron 15 of the NPAT gene (p = 4.6 × 10−3) at approximately 54 kb upstream of the ATM gene." (PMID 27796716, 2017). "Herein we investigated the ATR-Chk1 and ATM-Chk2 signalings in male breast cancer (MBC)." (PMID 28808232, 2017). "Here we examined whether ATM inhibition may sensitize breast cancer lines to PARP inhibitors, as well as whether the functional status of 53BP1 may affect the sensitivity of ATM-deficient tumors to these inhibitors." (PMID 27613518, 2016). "Finally, we demonstrated that miR-302b negatively regulates E2F1 and, indirectly, ATM, using two different cellular models of breast cancer, BT-549 (TNBC) and T47D (luminal breast cancer)." (PMID 26623722, 2016). "This difference is statistically significant (P =0.01) and supports the presence of a strong genetic component in the ATM carriers with early-onset breast cancer, also considered that the BRCAPRO score for the BRCA positive cases is very similar to ATM positive ones (50.1 % vs. 52.2 %)." (PMID 27599564, 2016). "ATM c.7271T>G (p.Val2424Gly) was identified in 12 cases and 1 control in studies participating in BCAC, all of European origin, giving evidence of association with breast cancer risk (p=0.0012)." (PMID 27595995, 2016). "ATM alteration is also common in solid tumors, including breast cancer, gastric and lung cancer." (PMID 27613518, 2016). "For European women, strong evidence of association with breast cancer risk was observed for PALB2 c.1592delT OR 3.44 (95% CI 1.39 to 8.52, p=7.1×10−5), PALB2 c.3113G>A OR 4.21 (95% CI 1.84 to 9.60, p=6.9×10−8) and ATM c.7271T>G OR 11.0 (95% CI 1.42 to 85.7, p=0.0012)." (PMID 27595995, 2016). "miR-421 induced ATM down regulation was also reported in breast cancer." (PMID 27016414, 2016). "al. used ATM sequence alterations located within exons or in short intron regions flanking each exon that encompass putative splice site regions as predictor for late normal tissue responses in breast cancer patients treated with radiotherapy." (PMID 27557076, 2016).
breast cancer (continued). "Evaluation of the histopathologic features of the breast cancers developed in the seven identified ATM carriers showed the presence of estrogen and progesterone receptors and the absence of HER2 receptor in four out of five cases that have been tested, confirming our previous results." (PMID 27599564, 2016). "In CD44+/CD24− stem-like cells, compared with other cell populations from breast cancer, the expression of ATM was significantly increased and the employment of an ATM inhibitor reversed their resistance to radiotherapy, suggesting the importance of ATM signaling in CSC formation." (PMID 27418953, 2016). "Lastly, in radioresistant subpopulations of breast cancer cells induced by irradiation, ATM, a protein activated by KAT5 acetylation, is hyperactivated and mediates stabilization of ZEB1, another well known EMT inducer, in breast cancer and other types of solid tumours." (PMID 27581651, 2016). "In addition, mutations in the CHEK2, ATM and BRIP1 genes confer a moderate lifetime risk of breast cancer but are rare and account for less than 5 % of familial breast cancer cases." (PMID 26553136, 2015). "Even though ATM is considered a moderate risk (20–25%) breast cancer predisposition gene, two specific mutations (c.7271T > G and IVS10-6T > G) were estimated to confer a 60% cumulative lifetime risk of breast cancer." (PMID 26484312, 2015). "Our group recently analyzed exome sequencing data from breast cancer samples, including one of the cases (M294) included here, and our preliminary (unpublished) results identified a larger number of ATM alterations compared with the data obtained from SSCP screening and direct DNA sequencing." (PMID 25625042, 2015). "Thus, at present, data related to the ATM gene in sporadic breast tumors are limited; thus, it is difficult to make an adequate assessment of its role in sporadic breast cancer." (PMID 25625042, 2015). "In the present study, we examined DNA from a series of 100 breast cancer patients without a family history of breast cancer and 100 healthy individuals for ATM gene mutations." (PMID 25625042, 2015). "Likewise, human breast cancer cells in which the levels of ATM had been depleted formed fewer lung tumors than normal breast cancer cells when they were transplated into mice." (PMID 26030852, 2015). "Finally, ATM-depletion in human breast cancer cells reduced lung tumors in a mouse xenograft model and clinical data validated IL-8 in lung metastasis." (PMID 26030852, 2015). "This may be secondary to decreased ATM levels in HCT-116 cells since depletion of ATM in breast cancer cells confers sensitivity to PARP inhibition." (PMID 26257651, 2015). "Also 50% of the treated population showed significant increase in expression of ATM levels which is generally downregulated in the breast cancer." (PMID 26176230, 2015). "The known high risk susceptibility genes for breast cancer, e.g. BRCA1, BRCA2, ATM, and PALB2, are responsible for approximately 20% of the hereditary cases, but several unknown breast cancer–predisposing genetic factors still exist." (PMID 25029565, 2014). "In these studies, the subpopulation of CD44+/CD24−/low cells, enriched for CSCs, of two breast cancer cell lines and the primary culture of patient breast cancer cells, demonstrated enhanced expression of phosphorylated ATM after radiation, which correlates with increased radioresistance." (PMID 24681585, 2014). "Interestingly, according to the tumor suppressor activity, ATM was downregulated in 55% of 119 patients with breast cancer, compared with adjacent normal breast tissues." (PMID 25247188, 2014).
breast cancer (continued). "Interestingly, we firstly discovered that the altered ATM signaling pathway, which was recently found related to reactive oxidative stress (ROS), is abnormally activation in the early stage of breast cancer." (PMID 23577100, 2013). "The altered ATM signaling pathway is abnormally active in the early stage of breast cancer." (PMID 23577100, 2013). "In the current studies, we assessed whether ATM depletion by RNA interference sensitize cells from breast cancer lines to PARP inhibitors." (PMID 24252502, 2013). "In a 2-stage case-control study Ye et al84 reported that the ATM polymorphisms rs1800054, rs1800058, rs664143, rs228589, and rs1003623 had no role in breast cancer." (PMID 23318652, 2013). "Despite this link between reduced ATM levels and breast cancer, deficiencies in the ATM protein are not frequently observed in non-familial breast cancer populations." (PMID 23741392, 2013). "In this study, we examined whether ATM inactivation in breast cancer cell lines confers sensitivity to PARP inhibitors." (PMID 24252502, 2013). "The ATM expression is significantly reduced in many breast carcinomas, and found no ATM mutation in that cell line." (PMID 24324828, 2013). "Inhibition of ATM could be an effective treatment to attenuate the radiation resistance of the CIC of breast cancer." (PMID 21935375, 2011). "However, activation of ATM signaling was significantly increased in CD44+/CD24−or low cells compared to non- CD44+/CD24−or low cells in both from breast cancer cell lines and primary human breast cancer cells." (PMID 21935375, 2011). "Collectively, our results uncover a new regulatory mechanism of ATM expression in breast cancer." (PMID 21980462, 2011). "Our results indicate that ATM D1853N polymorphism is not a risk factor for developing breast cancer." (PMID 20799949, 2010). "From the results of this small pilot study we propose a tentative ATM threshold of ~55% for risk of clinical radiosensitivity for breast cancer patients compared to the mean for non-reactor controls." (PMID 20678261, 2010). "In the same year, we described the first heterozygous ATM missense mutation causing dominant negative effects in breast cancer including cellular radiosensitivity and reduced ATM kinase activity but no obvious reduction in the level of the ATM protein." (PMID 20678261, 2010). "We found that ATM missense mutations, those detected in our study, do not by themselves contribute to an increased risk of breast cancer after exposure to radiation." (PMID 17428320, 2007). "The impact of variation in the ATM gene on the level of radiation induced side effects: costal fractures, subcutaneous and lung fibrosis, pleural thickening, development of telangiectasias and atrophy, was studied in the Norwegian breast cancer patients." (PMID 17623063, 2007). "In line with two out of three reports, we found an elevated – but not significant – risk of breast cancer in carriers of the rare 4258 T allele in the ATM gene." (PMID 17132159, 2006). "Previous mutation screening studies have indicated that mis-sense mutations in the ATM gene – rather than protein-truncating mutations – are over-represented in patients with breast cancer compared with the general population." (PMID 17132159, 2006). "Yet, not all studies confirmed the associated breast cancer risk conferred by being an ATM heterozygous mutation carrier." (PMID 16622469, 2006).